GRIN1 (glutamate ionotropic receptor NMDA type subunit 1)
Diseases named in the same sentence as GRIN1 in open-access papers (continued):
Sharing a sentence is not in itself a finding about the gene and the disease.
depression (29 papers, 2014 to 2026). "Increased Grin1 mRNA expression was previously associated with reduced depression-like behavior in a mouse model of neglect." (PMID 33628784, 2021). "On the other hand, in the frontal cortex, BDNF deficiency, which occurs under chronic stress and is one of the leading causes of depression, also increased the density of GRIN1, GRIN2A and GRIN2B genes in the early stages of development." (PMID 32585886, 2020). "Based on these scores, GRIN1 (rs4880213) was significantly associated with depression and disruptive behavior." (PMID 26819771, 2016). "One such study had shown significant association of GRIN1 (rs4880213) with depression." (PMID 31018568, 2019). "After the multiple comparison correction by 1,000 permutation tests, GRIN1 (rs4880213) was significantly associated with depression (P = 0.04) and disruptive behavior (P = 0.04), and GRIN2B (rs7301328) was significantly associated with disruptive behavior (P = 0.05)." (PMID 26819771, 2016). "Genetic changes in Grin1 may increase the risk of depression." (PMID 37089558, 2023). "PPI analysis identified Grin1 and Gria1 as the most central genes in the PPI network; these genes have been previously linked to depression." (PMID 37089558, 2023). "Cases of disruptive behavior and depression were notably less in subjects who had the T/T GRIN1 genotype (SNP rs4880213) than in the patients of the other two groups." (PMID 35186144, 2022). "Further epigenetic work showed that methylation in GRIN1 was a significant predictor of depression in a sample of maltreated children." (PMID 32585886, 2020). "Results showed that methylation in three genes were considered significant predictors of depression, including Tubulin Polymerization Promoting Protein (TPPP), DNA-Binding Protein Inhibitor-3 (ID3), and Glutamate N-Methyl-d-Aspartic Acid Receptor (GRIN1)." (PMID 30634536, 2019). "Three genes emerged as predictors of depression in combination with ELA: DNA-Binding Protein Inhibitor ID–3 (ID3); and Tubulin Polymerization Promoting Protein (TPPP); and the neurotransmitter gene glutamate receptor, ionotropic N-methyl-D-aspartate 1 (GRIN1)." (PMID 30984237, 2019). "Methylation in four genes developed as predictors of depression: ID3, NMDA, GRIN1, and TPPP." (PMID 30081481, 2018). "Behavioral differences in the EPM and FST tests showed that these genes, ID3, GRIN1, and TPPP, could predict anxiety and depression." (PMID 28785583, 2017).
Intellectual disability (21 papers, 2015 to 2025). "We investigate the neurophysiological consequences of the Y647S GRIN1 variant in the transmembrane region of the GluN1 NMDAR subunit that causes intellectual disability and epilepsy in a patient." (PMID 41602908, 2025). "With pathogenic GRIN1 variants first diagnosed in two patients with intellectual disability in 2011, pathogenic GRIN1 variants have been identified in many neurological disorders." (PMID 37396784, 2023). "Clinical features of the three patients harboring the GRIN1 gene variants described in this study include severe intellectual disability, developmental delay, and hypotonia." (PMID 37734923, 2023). "Deep clinical phenotyping of patients harbouring disease-associated GRIN1-DNV confirmed the severity of the associated clinical scenarios that cause neurodevelopmental alterations with invariable presence of intellectual disability and motor alterations." (PMID 34884460, 2021). "GRIN1 mutation associated with intellectual disability alters NMDA receptor trafficking and function." (PMID 34035826, 2021). "Mutations in GRIN1 [which encodes the GluN1 (NR1) subunit of NMDAR] have been associated with a phenotype consisting of severe intellectual disability, seizures, hyperkinetic and stereotyped movement disorders, and dysmorphic features." (PMID 32116982, 2019). "Deleterious missense and nonsense variants in GRIN1, GRIN2A-D, and GRIN3A-B cause encephalopathies that are sometimes first diagnosed as intellectual disability, global developmental delay, epilepsy, autism, and/or schizophrenia." (PMID 32807843, 2021). "We found that Grin1 expression was restored in adulthood, and molecular analysis, cellular function and cognitive functions were quantified as outputs to measure the ability to reverse intellectual disability." (PMID 32807843, 2021). "We compared the positions of the 11 polymicrogyria-associated GRIN1 mutations with 16 different heterozygous proven (or likely) de novo GRIN1 mutations previously reported in 23 patients with non-syndromic intellectual disability and epileptic encephalopathy." (PMID 29365063, 2018). "Investigators from Yokohama City University and other medical centers in Israel and Japan reported mutations on N-methyl-D-aspartate (NMDA) receptors subunit GRIN1 (GluN1) identified in patients with nonsyndromic intellectual disability and early-onset epileptic encephalopathy." (PMID 26933583, 2015). "Mutations in GRIN1 (which encodes the GluN1 subunit), GRIN2B (GluN2B), and GRIN2D (GluN2D), expressed during embryonic development, display more severe clinical phenotypes, including severe intellectual disability and developmental delay, than GRIN2A (GluN2A) mutations." (PMID 32197322, 2020). "For example, GRIN1 and GRIN2B patients can present with mild or severe intellectual disabilities." (PMID 39535073, 2025).
Anxiety (17 papers, 2013 to 2024). Intense feelings of nervousness, tension, or panic often arise in response to interpersonal stresses. "Male animals born from mothers fed the palatable diet, and who continued with this diet after weaning, exhibited anxiety associated with an overexpression of the mRNA of Grin1, Gria1 and Grm5 glutamate receptors in the prefrontal cortex." (PMID 32575416, 2020). "This study demonstrated that the Grin1Rgsc174/Grin1+ mutation causes abnormal anxiety-like behaviors, a deficiency in fear memory, and a decreased startle amplitude in mice." (PMID 23688147, 2013). "In opposite to Grin1-KD mice, MK-801-treated animals performed normally on T1-T4 trials, excluding potential side effects of MK-801 on motor functions or anxiety." (PMID 39612588, 2024). "Curiously, in young adult rats with anxiety-like behaviors, the genes Grin1 and Grik2, which code for subunits of different glutamate receptors, were differentially regulated compared with controls of the same age." (PMID 35998298, 2023). "Grin1Rgsc174/Grin1+ mice exhibited behavioral abnormalities, including increased locomotor activity, abnormal anxiety-like behavior, a mild deficit in working memory, and severely impaired fear memory." (PMID 23688147, 2013). "In contrast, in the light/dark transition test, Grin1Rgsc174/Grin1+ mice displayed a decreased number of transitions between the light and dark chambers, which is a well-validated index of anxiety-like behavior." (PMID 23688147, 2013). "The number of transitions between the chambers decreased in the light/dark transition test, suggesting increased anxiety-like behavior in Grin1Rgsc174/Grin1+ mice." (PMID 23688147, 2013). "The GRIN1 (glutamate receptor, ionotropic, NMDA1) gene plays an important role in excitatory neurotransmission, and the increase of its expression has been associated with anxiety in response to stress in mice." (PMID 32316129, 2020). "Grin hypomorphic, Grin1(D481N)/Grin1+, and our mice consistently displayed increased time spent in open arms in the elevated plus maze or zero maze tests, suggesting decreased anxiety-like behavior in these mice." (PMID 23688147, 2013). "Grin1Rgsc174/Grin1+ mice exhibited increased time spent in the open arms and a greater number of entries into the open arms in the elevated plus maze test, which is generally interpreted as a decrease in anxiety-like behavior." (PMID 23688147, 2013). "Grin1Rgsc174/Grin1+ mice showed abnormal behaviors related to these disorders, including increased locomotor activity, severely impaired fear memory, mild deficit in working memory, and abnormal anxiety-like behavior." (PMID 23688147, 2013). "Further studies are needed to determine whether anxiety is increased or decreased in Grin1Rgsc174/Grin1+ mice." (PMID 23688147, 2013). "Mutant mice overexpressing casein kinase 1 (CK1δ) and Grin1 (glutamate receptor, ionotropic, NMDA1) showed increased locomotor activity and abnormal anxiety-like behavior." (PMID 24528488, 2014). "We find that disruption of Grin1 in CRF neurons did not affect baseline levels of anxiety, locomotion, pain sensitivity or exploration of a novel object." (PMID 25340785, 2014). "We found that knockdown of Grin1 in CRF containing neurons decreases the expression of Grin1 in the amygdala and enhances fear memory formation and retention without effecting anxiety, activity level, pain sensitivity or novelty seeking behaviors." (PMID 25340785, 2014). "Preclinical transgenic mice studies not isolated to the CeA where they used the mouse model Grin1 D481N, which has low binding affinity for glycine in the R1 subunit, showed that Grin1 D481N mice that were exposed to alcohol had fewer signs of anxiety-like behaviors compared to wildtype mice." (PMID 38352404, 2024).
Anxiety (continued). "Social and cognitive deficits are largely, but not completely rescued upon adult reinstatement of Grin1 and fully rescued upon Shank3 reinstatement, but motor and anxiety deficits are only partially rescued upon Grin1 reinstatement and not rescued upon Shank3 reinstatement." (PMID 36304100, 2022). "Manipulation of CRF containing Grin1 neurons did not affect anxiety-like behavior." (PMID 25340785, 2014). "We find disruption of Grin1 in CRF containing neurons enhances fear memory acquisition and retention without effecting baseline measures of anxiety." (PMID 25340785, 2014).
psychosis (17 papers, 2015 to 2025). "The genetic variation of GRIN1 provides a good example for the genetic association with MA dependence and its resultant psychosis." (PMID 30519197, 2018).
Alzheimer disease (13 papers, 2013 to 2026). A progressive, neurodegenerative disease characterized by loss of function and death of nerve cells in several areas of the brain leading to loss of cognitive function such as memory and language. "Maf1 regulates the expression of NMDAR1 by binding to the promoter of the Grin1 gene and could represent a potential therapeutic target for Alzheimer’s disease." (PMID 38226680, 2024). "We identified several proteins involved in the Alzheimer's disease pathway, including NMDA receptor (NMDARs) subunits (GRIN1, GRIN2B, and GRIN2D)." (PMID 40047119, 2025). "Especially, GRIN1 and MAPK1 interacted with APP protein and located in the key point of the “Alzheimer’s disease” pathway." (PMID 33784489, 2021).
autism (11 papers, 2013 to 2026). Persistent deficits in social interaction and communication and interaction as well as a markedly restricted repertoire of activity and interest as well as repetitive patterns of behavior. "GRIN1 knockdown mice have been identified and used as an autism model, and loss of GRIN1 activation in corticotropin-releasing factor neurons in male naïve mouse increases social stress." (PMID 37537543, 2023). "For example, mutations in Grin1, Myh10, Mapk1, and Atp1a3 were found in autism patients or mice." (PMID 32033586, 2020).
developmental delay (9 papers, 2017 to 2023). "GRIN1 positive patients present in almost all cases with severe developmental delay, cognitive dysfunction, and profound ID since early infancy." (PMID 29086067, 2017).
autism spectrum disorder (8 papers, 2017 to 2025). A spectrum of developmental disorders that includes autism, and Asperger syndrome. "Similarly, despite the presence of severe verbal communication deficits, GRIN1-DNV cohort exhibits a variable manifestation of autism spectrum disorders (ASD) traits (6 out of 15)." (PMID 34884460, 2021).
ischemia (8 papers, 2015 to 2025). A hypoperfusion of the BLOOD through an organ or tissue caused by a PATHOLOGIC CONSTRICTION or obstruction of its BLOOD VESSELS, or an absence of BLOOD CIRCULATION. "Our findings were inconsistent with previous findings that GRIN1 expression was repressed by REST in the ischemia-induced neuronal death model." (PMID 34106879, 2021). "For example, excessive activation of NMDA receptor-mediated glutamatergic signaling (GRIN1) in early ischemia may lead to intracellular calcium overload and a cascade of apoptotic and necrotic events." (PMID 40896336, 2025).
Epileptic encephalopathy (7 papers, 2015 to 2025). A condition in which epileptiform abnormalities are believed to contribute to the progressive disturbance in cerebral function. "Next generation sequencing analysis of 88 unsolved epileptic encephalopathies revealed 4 patients with 4 de novo missense GRIN1 mutations." (PMID 26933583, 2015). "Mutations in genes encoding NMDAR subunits, such as GRIN1, GRIN2A, GRIN2B, GRIN2C, and GRIN2D, have been linked to various epileptic phenotypes, ranging from focal and generalized seizures to severe epileptic encephalopathies." (PMID 39596430, 2024). "For example, mutations in GRIN1 are associated with early infantile encephalopathy and developmental delay, while GRIN2A and GRIN2B mutations contribute to epilepsy syndromes like Landau–Kleffner syndrome and epileptic encephalopathy, respectively." (PMID 39596430, 2024).
ischemic stroke (7 papers, 2017 to 2025). A stroke disorder caused by obstruction of blood flow to the brain, due to thrombotic (local blood clot formation) or embolic (due to a blood clot or other material traveling from another site) event. "Therein, although GRIN1 expression declines after REST up-regulation in the ischemic stroke, the different circumstances, especially the different cell types and cultural environments, might lead to this discrepancy." (PMID 34106879, 2021).
bipolar disorder (6 papers, 2013 to 2021). A disorder of the brain that causes unusual shifts in mood, energy, activity levels and the ability to carry out day-to-day tasks. "Previous studies show that GRIN1 (rs11146020) was strongly associated with bipolar disorder and depressive symptoms." (PMID 26819771, 2016). "Significant associations have also been reported between GRIN1 and bipolar disorder, as well as between GRIN2B and ADHD." (PMID 23688147, 2013). "The gene GRIN1, differentially expressed between PTSD-Controls, encodes a NMDA receptor involved in activation of the pre-frontal cortex and previously linked to Bipolar Disorder." (PMID 33897478, 2021).
Parkinson disease (6 papers, 2013 to 2025). A progressive degenerative disorder of the central nervous system characterized by loss of dopamine producing neurons in the substantia nigra and the presence of Lewy bodies in the substantia nigra and locus coeruleus. "The top-five pathways significantly enriched for GRIN1 were neuroactive ligand–receptor interaction, arginine and proline metabolism, Parkinson’s disease, ribosome, and basal cell carcinoma." (PMID 40740189, 2025). "We also found that GNAQ, GRIN1, and PLCB1 are in both Huntington's and AD but not in Parkinson's pathways, and SNCA is in both Parkinson's and AD but not Huntington's pathways." (PMID 31068785, 2019).
diabetes (5 papers, 2013 to 2025). "Dextromethorphan, a GRIN1 antagonist, has been shown to inhibit neo-intima and atherosclerosis formation in mice and has shown promise as an adjunct treatment for diabetes." (PMID 35628106, 2022). "It is worth noting that the roles of PTPRN2, ASTN2, GRIN1, SLC6A18, and PDE2A in influencing FPG levels or diabetes had previously been suggested." (PMID 37461060, 2023). "However, in contrast to the results of this study, another study using Wistar rats found that GRIN1 mRNA expression was increased after 1 and 4 weeks of diabetes and did not change after 12 weeks, and GRIN2C mRNA levels did not change at any time point." (PMID 23878504, 2013).
encephalopathies (5 papers, 2021 to 2023). "In fact, mutations in GRIN1 are related to a variety of infantile-onset seizures (GoF mutations) and encephalopathies (LoF variants)." (PMID 38003469, 2023). "Mice with a global LOF GRIN1 allele showed deficits in cognitive behaviors, similar to those seen in GRIN1 encephalopathies." (PMID 35936491, 2022). "In this study, we report one patient who presented with early onset severe encephalopathy, and striking stimulus-induced myoclonus due to a de novo pathogenic variant in the GRIN1 gene." (PMID 34413877, 2021). "This structural-functional stratification provides relevant insights of genotype-phenotype association, contributing to future precision medicine of GRIN1-related encephalopathies." (PMID 34884460, 2021). "The knockdown of Grin1 results in viable mutant mice with deficits in cognitive behaviours that parallel the symptoms of GRIN1 encephalopathy." (PMID 32807843, 2021).